DLX4 (distal-less homeobox 4)
Diseases named in the same sentence as DLX4 in open-access papers (continued):
Sharing a sentence is not in itself a finding about the gene and the disease.
acute myeloid leukemia (2 papers, 2021 to 2023). Acute myeloid leukemia (AML) is a group of neoplasms arising from precursor cells committed to the myeloid cell-line differentiation. "DLX4 hypermethylation was a prognostically adverse indicator in acute myeloid leukemia." (PMID 37744456, 2023).
dental caries (2 papers, 2021 to 2023). The decay of a tooth, in which it becomes softened, discolored, and/or porous. "These lines of evidence suggest that both DLX3 and DLX4 may play important roles in the dental caries process by the regulation tooth development." (PMID 34311721, 2021). "In summary, this study found multiple associations near genes that may play important roles in dental caries, such as TAS2R38, TAS2R3, TAS2R4, TASR25, DLX3 and DLX4, several of which have plausible biological functions relevant to tooth development and cariogenesis." (PMID 34311721, 2021). "Both distal-less homeobox 3 (DLX3), which plays a role in odontogenesis, and DLX4, which is highly expressed in human dental pulp cells (DPC), might play an important role in the process of dental caries by regulating tooth development." (PMID 37275173, 2023).
non-small cell lung carcinoma (2 papers, 2021 to 2022). A group of at least three distinct histological types of lung cancer, including non-small cell squamous cell carcinoma, adenocarcinoma, and large cell carcinoma. "Moreover, DLX4 hypermethylation, with a role in silencing DLX4 expression, is associated with disease evolution in uterine cervical low-grade squamous intraepithelial lesions (LSILs) and non-small cell lung cancer (NSCLC)." (PMID 35883028, 2022).
Alzheimer disease (1 paper, 2024). A progressive, neurodegenerative disease characterized by loss of function and death of nerve cells in several areas of the brain leading to loss of cognitive function such as memory and language. "Additionally, DLX4 is linked to neurogenesis and Alzheimer's disease." (PMID 39020437, 2024).
craniofacial clefts (1 paper, 2022). "Some of these proteins like Homeobox Protein BarH-like 1 (BARX1), Distal-Less Homeobox 4 (DLX4), Forkhead Box E1 (FOXE1), Homeobox Protein Hox-B3 (HOXB3), and Muscle Segment Homeobox 2 (MSX2) have been associated with the formation of craniofacial clefts." (PMID 37733420, 2022).
myeloid leukemia (1 paper, 2022). A clonal proliferation of myeloid cells and their precursors in the bone marrow, peripheral blood, and spleen. "Previously, we reported the expression of DLX4 isoforms (BP1 and DLX7) in myeloid leukemia, but the functional role of DLX4 isoforms remains poorly understood." (PMID 35883028, 2022).
thyroid cancer (1 paper, 2023). "We found five TAD blocks with CoMut genes/events specific to ATC with certain mutation frequency in The Cancer Genome Atlas Thyroid Cancer (TCGA-THCA) cohort, including CoMut pairs MAST/NSUN4, AM129B/TRUB2, COL5A1/PPP1R26, PPP1R26/GPSM1/CCDC183, and PRAC2/DLX4." (PMID 36609218, 2023).
tumor (19 papers, 2010 to 2024). "As for DLX4, its overexpression was described in numerous tumor types (including AML) in association with tumor progression and/or invasion." (PMID 35148810, 2022). "This study also revealed that DLX4 knockdown blocked the cell cycle of NPC at G1 phase, suggesting the anti-tumor effect of DLX4 knockdown on NPC." (PMID 37744456, 2023). "The results support the tumor suppressive role of DLX4 in human cancers, including myeloid malignancies." (PMID 35883028, 2022). "We therefore, compared level of DLX4 in normal prostate epithelial cells and tumor cells from cancers of different GS." (PMID 26560244, 2015). "DLX4, a homeobox gene, overexpressed in several cancers, was shown to reduce sensitivity of tumor cells to TOP2A poisons by stimulating repair of DSB by non-homologous end joining." (PMID 26560244, 2015). "This activity of DLX4 protected tumor cells against DNA damaging chemotherapeutic agents such as doxorubicin and etoposide." (PMID 25924901, 2015). "Deregulation of the expression of Dlx genes, including Dlx-4 and Dlx-5, was found in human solid tumors and hematologic malignancies and indicates an important role(s) of Dlx in tumor growth and progression." (PMID 21917150, 2011). "DLX4 is also involved in switching TGFβ signaling from tumor suppressing to tumor promoting." (PMID 34203994, 2021). "In terms of specific mechanisms, DLX4 could promote tumor progression through regulating metastasis, modulating responsiveness to targeted drugs, and controlling angiogenesis." (PMID 34124141, 2021). "Mechanistically, DLX4 was found to interact with Ku proteins to promote DNA-dependent protein kinase activity and end-joining repair of DSBs, thereby, reducing sensitivity of tumor cells to TOP2 poisons." (PMID 34203994, 2021). "Consistent with our previous studies, DLX4 increased tumor microvessel density." (PMID 25924901, 2015). "It is possible that DLX4 might similarly protect tumor cells against the genotoxic effects of high NO levels by stimulating repair of DNA damage caused by NO metabolites." (PMID 25924901, 2015). "Some targets, such as DLX4, NDRG3, WNT1, MYC, CREB1, and SIRT6, are involved in tumor or cell proliferation." (PMID 39618816, 2024). "Our results further showed that downregulation of DLX4 suppressed YB-1 expression, which further suppressed CKS2 expression, thereby suppressing tumor growth of NSCLC." (PMID 37744456, 2023). "We found that downregulation of DLX4 inhibited YB-1 expression, which in turn suppressed CKS2 expression, thus inhibiting tumor growth." (PMID 37744456, 2023). "Downregulation of DLX4 inhibited YB-1 expression, and suppressed CKS2 expression, thereby inhibiting tumor growth of NSCLC." (PMID 37744456, 2023). "Our study demonstrated that DLX4 isoforms BP1 and DLX7 have opposite functions in leukemogenesis, with BP1 playing an oncogenic role whereas DLX7 plays a tumor suppressive role in leukemogenesis." (PMID 35883028, 2022). "The results revealed that the mRNA expression levels of DLX4, FBN1, HIC1, HOXB9, ONECUT2, and SIX1 were significantly different between tumor samples and normal tissues, which were consistent with the results from TCGA." (PMID 35095892, 2021). "Our findings that the stimulatory effects of DLX4 on VEGF-A production and tumor angiogenesis are abrogated when iNOS is inhibited support the conclusion that these stimulatory effects of DLX4 are primarily mediated via its induction of iNOS." (PMID 25924901, 2015). "Deregulation of DLX genes, including DLX4 and DLX5, was found in human solid tumors and hematologic malignancies, which indicated that DLX played an important role in tumor growth and progression." (PMID 26052251, 2015).
tumor (continued). "Although the mechanism and pathway of DLX4 and its involvement in IBC maintenance and progression remains unknown, it has been suggested to be a marker for tumor aggressiveness." (PMID 30131852, 2018). "In subsequent experiments, we sought to determine whether DLX4 stimulates NO and VEGF-A production in tumor cells by inducing iNOS." (PMID 25924901, 2015). "Our data indicate that this is not the case in PCa, as the level of DLX4 does not increase with the tumor grade but remains similar to that in normal epithelial cells." (PMID 26560244, 2015). "The distal-less homeobox gene 4 (DLX4), a member of the DLX family widely expressed in various cancers, has also been shown to bind to regulatory regions of the Twist1 gene and enhances tumor migration, invasion, and metastasis in cell models and tumor tissues." (PMID 28099910, 2017).
cancer (15 papers, 2012 to 2024). A tumor composed of atypical neoplastic, often pleomorphic cells that invade other tissues. "CNTN1, a DLX4 isoform, has been implicated in cell differentiation and early development, and its expression is frequently dysregulated in cancer." (PMID 29673312, 2018). "Within the list of top differentially expressed genes, in the UCHL1 KDs we found downregulation of the Wnt targets POSTN, SP7, and DLL1, of the transporter ABCA4, of the homeobox gene DLX4, and of genes recently linked to cancer progression ACTA2, AQ4, GRAP2, and ALK." (PMID 28472177, 2017). "Beta Protein 1(BP1), an isoform of DLX4, belongs to the homeobox family of genes, master regulatory genes implicated in early development and cell differentiation that are frequently deregulated in cancer." (PMID 27449292, 2016). "For example, in the DLX4 gene module, connections among DLX4, the known cancer gene ABL1, and four candidate AML genes (SP1, FYN, GRB2, and SMAD2) co-occurred in multiple patients." (PMID 39013885, 2024). "Other significant genes, including RIPOR2, FAM30A, DLX4 and LAT, are associated with inflammatory/immune processes and various cancer etiologies." (PMID 39020437, 2024). "In the previous study, DLX4 affected the progression of cancer by mediating the expression of YB-1 and CKS-2." (PMID 37744456, 2023). "DLX4 was originally identified as a β-globin gene suppressor in red blood cells, which plays critical roles in several types of cancers." (PMID 37744456, 2023). "Studies have confirmed that DLX4 promotes proliferation, cell cycle arrest, and invasion of carcinoma cells, and the expression of YB-1 is decreased in DLX4 depletion cells, while the expression of YB-1 is increased in DLX4 overexpression cells." (PMID 37744456, 2023). "The expression pattern of DLX4 and its clinical significance have been demonstrated in several human cancers." (PMID 35883028, 2022). "Overexpression of DLX4 leads to cancer migration, invasion, and metastasis by driving the expression of TWIST." (PMID 31739630, 2019). "As a positive control, invasive moderately differentiated ductal carcinoma was stained with the DLX4 antibody." (PMID 30131852, 2018). "DLX4 (homeobox protein DLX-4) is a nuclear transcription factor that is overexpressed in several cancer types." (PMID 23213280, 2012). "We further investigated the expression of DLX4 in different types of cancers through the database." (PMID 37744456, 2023). "Moreover, the gene set enrichment analysis (GSEA) was used to identify the enriched cancer hallmark pathways, and the curves showed the top enrichment pathways for BARX1 and DLX4." (PMID 34124141, 2021). "Other significant genes, such as LAT, DLX4 and POLD4, are related to inflammatory/immune processes and various cancer types." (PMID 39020437, 2024). "Functional experiments were conducted to verify the cancer-promoting effect of BARX homeobox 1 (BARX1) and distal-less homeobox 4 (DLX4) in ccRCC, and Western blot was performed to explore their downstream pathways." (PMID 34124141, 2021). "DLX4 induces cancer cells to undergo epithelial-to-mesenchymal transition (EMT) via TWIST, and the overexpression of DLX4 increases TWIST expression in cancer cell lines, leading to enhanced migration and invasion." (PMID 38317839, 2024). "DLX4, widely expressed in different types of cancer but absent in most normal adult tissues, induces EMT through directly binding to regulatory regions of TWIST gene." (PMID 35095892, 2021).
DLX4 also shares sentences with these, for which no sentence is quoted: cleft palate (2 papers); hematologic malignancies (2); inflammatory breast carcinoma (2); leukemia (2); prostate adenocarcinoma (2); prostate carcinoma (2); breast tumor (1); chronic myeloid leukemia (1); colon cancer (1); colorectal cancer (1); endothelial dysfunction (1); lip (1); psychiatric disorder (1); renal carcinoma (1).